IFRD1 (interferon related developmental regulator 1)
Description:
Could play a role in regulating gene activity in the proliferative and/or differentiative pathways induced by NGF. May be an autocrine factor that attenuates or amplifies the initial ligand-induced signal (By similarity).
Synonyms: PC4; TIS7
Tractability: Antibody: the Human Protein Atlas places it where antibodies can reach. PROTAC: ubiquitination databases record sites on it.
Gene: Protein-coding gene on chromosome 7 (112,422,887 to 112,481,017, forward strand). Ensembl gene ENSG00000006652.
Subcellular location (Human Protein Atlas): Plasma membrane; Cytosol; Endoplasmic reticulum
Gene Ontology:
Biological process: myoblast fate determination; cell differentiation
Cellular component: nucleus; cytoplasm
Genetic constraint (gnomAD): Loss-of-function variants: 19 observed, 34.19 expected, observed/expected ratio (o/e) 0.56, 90% interval 0.39 to 0.81. The upper end of that interval is the gene's LOEUF score, 0.81, which puts it in group 3 of 6, group 1 being the genes least tolerant of losing a copy. Missense variants: 431 observed, 469.79 expected, observed/expected ratio (o/e) 0.92, 90% interval 0.85 to 0.99. Synonymous variants: 152 observed, 164.83 expected, observed/expected ratio (o/e) 0.92, 90% interval 0.81 to 1.05.
Homologues: Orthologues: chimpanzee IFRD1 (99% identical), macaque IFRD1 (99% identical), rabbit IFRD1 (96% identical), dog IFRD1 (95% identical), pig IFRD1 (95% identical), mouse Ifrd1 (94% identical), rat Ifrd1 (94% identical), guinea pig IFRD1 (92% identical), tropical clawed frog ifrd1 (66% identical), zebrafish ifrd1 (60% identical), Drosophila melanogaster Ifrd1 (34% identical), Caenorhabditis elegans F58B3.6 (26% identical). Paralogues in human: IFRD2 (49% identical).
Diseases named in the same sentence as IFRD1 in open-access papers:
IFRD1 is named in the same sentence as 33 diseases in open-access papers, as found by Europe PMC text mining. Sharing a sentence is not in itself a finding about the gene and the disease. The quoted sentences say what the papers report.
breast carcinoma (4 papers, 2019 to 2024). "IFRD1 gene expression levels indicated increased risk in the outcome of Luminal A breast cancer patients, showing a role in the prognostic value for patient survival." (PMID 39765744, 2024). "The expression of AMOTL1 and IFRD1 was linked to an increased risk of breast cancer, whereas ARRB1 was associated with a protective effect." (PMID 37644433, 2023). "On the other hand, IFRD1 gene expression was higher in normal tissues than tumor tissues of breast cancer patients, indicating that the role of the immune system is present in any stage of carcinogenesis." (PMID 39765744, 2024). "Specific genes that have been identified as drivers of stemness of breast cancer stem cells, such as interferon‐related developmental regulator 1 (Ifrd1) and Stat1, were among the upregulated genes." (PMID 31069797, 2019). "Overall survival analysis showed that TNFAIP6, IFITM2, IFNGR1, and IRF6 expression levels were not significant, whereas IFRD1 (n = 568) indicated a significantly (p < 0.05) increased risk in Luminal A breast cancer patients, along with NFIL3 (n = 219) in Luminal B patients with similar significance." (PMID 39765744, 2024). "The heat map tables show the correlation between immune cell infiltrations and TNFAIP6, IFRD1, IFITM2, IFNGR1, IRF6, and NFIL3 in breast cancer." (PMID 39765744, 2024). "The protein expression levels of TNFAIP6, IFRD1, IFNGR1, and IRF6 were analyzed in 125 breast cancer samples and 18 normal samples by using the UALCAN dataset." (PMID 39765744, 2024). "We consulted the Human Protein Atlas Interactive Analysis to validate the expression of the core driver genes, including IDI1, BNIP3, IFRD1, COQ10B, and ZBTB10, at the protein and RNA levels in breast cancer." (PMID 34226298, 2021). "However, the correlation between ESR1 and IFRD1 was non-significant in breast cancer patients." (PMID 39765744, 2024). "There was a non-significant difference in the correlation between IFRD1 and ESR1 gene expression levels in breast cancer patients; additionally, those patients had significantly negative ER statuses, corroborating the lack of a relation between its action and the hormonal status of the patient." (PMID 39765744, 2024).
asthma (3 papers, 2021 to 2023). "IFRD1 regulates the pathogenesis of asthma and cystic fibrosis through mediating neutrophil function." (PMID 33658578, 2021).
Ataxia (3 papers, 2018 to 2025). Ataxia refers to impaired coordination of voluntary muscle movement. "We, therefore, supplemented the EOAD- control group with ataxia genotypes that were not reported with comorbid dystonia in literature (including ABHD12; IFRD1; KIAA0226; PHYH; TDP1; VWA3B; GTF2H5; FLVCR1; ACO2; HSD17B4; DNAJC3 gene mutations; PubMed and OMIM)." (PMID 33255407, 2020).
colon cancer (3 papers, 2019 to 2023). "It is reported that IFRD1 (known as interferon-related developmental regulator 1) encoded a protein related to interferon-γ and was significantly correlated with survival outcome in colon cancer." (PMID 37008945, 2023). "Studies by Lewis and others showed that IFRD1 is highly expressed in colon cancer and is negatively correlated with the 5-year survival time." (PMID 31138312, 2019).
cystic fibrosis (3 papers, 2015 to 2021). Autosomal recessive disorder caused by pathogenic variants in the CFTR gene (cystic fibrosis transmembrane conductance regulator), which encodes a chloride and bicarbonate channel expressed in epithelial cells, and follow the diagnosis criteria. "This was true for IFRD1 (a.k.a.PC4 and TIS7), an interferon-relateddevelopmental regulator that was reported to be a modifier gene for cystic fibrosis." (PMID 25621764, 2015).
glioma (2 papers, 2019 to 2023). A benign or malignant brain and spinal cord tumor that arises from glial cells (astrocytes, oligodendrocytes, ependymal cells). "CBX3, GUCY1A3, and IFRD1 have been reported in relation to some tumors but have been studied little in glioma." (PMID 31138312, 2019). "In our study, IFRD1 is specifically overexpressed in glioblastoma and suggests a poor prognosis in glioma." (PMID 31138312, 2019).
hepatocellular carcinoma (2 papers, 2024 to 2025). A malignant tumor that arises from hepatocytes. "Here, we disclose the critical role of interferon-related developmental regulator 1 (IFRD1) in the adaptive survival of hepatocellular carcinoma (HCC) cells during glutamine starvation." (PMID 38802351, 2024). "In hepatocellular carcinoma (HCC), interferon-related developmental regulator 1 (IFRD1) is upregulated by glutamine starvation to inhibit autophagy by promoting TRIM21-mediated degradation ATG14." (PMID 40735642, 2025).
craniosynostosis (1 paper, 2025). Craniosynostosis is defined as the premature fusion of one or more cranial sutures leading to secondary distortion of skull shape resulting in skull deformities with a variable presentation. "IFRD1 is involved in urothelial cell regeneration, skeletal muscle regeneration, and bone homeostasis and has been associated with a congenital anomaly (craniosynostosis) and growth." (PMID 41514760, 2025).
ductal carcinoma (1 paper, 2024). "The immunohistochemical analysis indicated that IFRD1 protein expression intensity was higher in normal breast tissue than in ductal carcinoma." (PMID 39765744, 2024). "This immunohistochemical analysis indicated that TNFAIP6, IFRD1, and IRF6 protein expression intensity was positive in normal breast tissue and ductal carcinoma." (PMID 39765744, 2024).
esophageal cancer (1 paper, 2024). A primary or metastatic malignant neoplasm involving the esophagus. "In the other clusters, the genes SCML4, HNRNPF, IFRD1, CSTA, ABL1, etc., have a causal relationship with esophageal cancer." (PMID 38434988, 2024). "Similarly, genes like SCML4, HNRNPF, IFRD1, CSTA, ABL1 in other immune cell clusters also exhibit a causal relationship with esophageal cancer." (PMID 38434988, 2024).
hypertriglyceridemia (1 paper, 2023). A laboratory test result indicating elevated triglyceride concentration in the blood. "The results presented here implicate that Ifrd1 and Ifrd2 play a up to now unknown role in the regulation of Cd36 and therefore possibly contribute to Cd36-related pathogenesis of human metabolic diseases, such as hypoglycemia, hypertriglyceridemia, and disordered fatty acid metabolism." (PMID 37603466, 2023).
liver cancer (1 paper, 2024). An epithelial or non-epithelial malignant neoplasm that arises from the liver. "We found that the relationships between IFRD1, ATG14, and H1.0 were intact in vivo liver cancer tissues, suggesting that the signaling pathway uncovered in vitro is clinically relevant." (PMID 38802351, 2024). "Further, immunofluorescence staining proved the differential expression patterns of IFRD1 and GLS1 in liver cancer tissue." (PMID 38802351, 2024).
lung disease (1 paper, 2013). "Discordant allele frequencies were identified between the pools using this strategy and indicated that alleles of IFRD1 may contribute to pulmonary disease severity." (PMID 23630497, 2013). "In a subsequent study, however, IFRD1 variants did not significantly associate with lung disease." (PMID 23630497, 2013).
Obesity (1 paper, 2023). Accumulation of substantial excess body fat. "Mice deficient in both Ifrd1 and Ifrd2 (dKO) had severely reduced adipose tissue and were resistant to high-fat diet-induced obesity." (PMID 37603466, 2023). "Experimental data presented here show that simultaneous depletion of Ifrd1 and of its orthologue Ifrd2, a protein recently identified as a translational inhibitor, caused severe reduction of adipose tissues and resistance against high fat-induced obesity in mice." (PMID 37603466, 2023). "It is possible that due to the reduced Cd36 expression levels in intestines, Ifrd1 Ifrd2 dKO mice accumulated lower amounts of body fat and were resistant to diet-induced obesity also because of limited intestinal fat uptake." (PMID 37603466, 2023).
pancreatitis (1 paper, 2026). Inflammation of the pancreas. "Using multiple in vivo and in vitro injury models, including cerulein-induced pancreatitis in mice and tunicamycin-induced ER stress in cell culture, we demonstrate that IFRD1 acts as a ribosome-salvaging factor, preventing ribosomes from degradation." (PMID 42146531, 2026).
periodontitis (1 paper, 2023). An acute or chronic inflammatory process that affects the tissues that surround and support the teeth. "MiR-200c directly targets 3′ UTRs of IL-6, IL-8, interferon-related developmental regulator 1 (Ifrd1), and chemokine (C-C motif) ligand 5 (CCL-5), and downregulated their expression in human periodontal ligament, gingival fibroblasts, and the periodontium of periodontitis rats." (PMID 37525201, 2023).
cancer (7 papers, 2015 to 2025). A tumor composed of atypical neoplastic, often pleomorphic cells that invade other tissues. "Together, our findings reveal how IFRD1 supports the adaptive survival of cancer cells under glutamine starvation, further highlighting the potential of IFRD1 as a therapeutic target in anti-cancer applications." (PMID 38802351, 2024). "Conversely, targeting IFRD1 in the glutamine-deprived state increases autophagy flux, triggering cancer cell exhaustive death." (PMID 38802351, 2024). "Nonetheless, further preclinical testing is required to confirm this point, together with additional studies to establish the relevance of IFRD1 in cancers other than HCC." (PMID 38802351, 2024). "COX-2, PD-L1 and IFRD1 have been reported to be subject to NMD degradation in other cancers." (PMID 41293174, 2025). "Furthermore, there was a positive correlation between IFRD1 gene expression and neutrophil infiltration in Basal, Luminal A, and Luminal B cancer patients and between IFRD1 gene expression and macrophage infiltration in Her2 and Luminal B patients." (PMID 39765744, 2024). "Similar observations are made in IFRD1-overexpressing HPV-induced cancer cells." (PMID 26055519, 2015). "Collectively, our data identify IFRD1 as a potential primary target for exploiting glutamine starvation strategies in HCC and perhaps other cancers." (PMID 38802351, 2024). "Immunohistochemistry and RNA expression analysis indicated that IDI1, BNIP3, IFRD1, and ZBTB10 were significantly differentially expressed in cancer and healthy tissues." (PMID 34226298, 2021).
tumor (6 papers, 2009 to 2026). "Further examination of the tumor tissues using immunohistochemical staining against Ki67 showed a marked reduction in mitotic cells associated with the tumor growth retardation observed in IFRD1 knockout tumors in mice fed glutamine-deficient chow." (PMID 38802351, 2024). "Notably, preclinical models confirmed that combined glutamine deprivation/CB-839 treatment with IFRD1 loss caused tumor regression in vivo." (PMID 38802351, 2024). "The GEPIA2 analysis results indicate that the top 5 key genes (Bcam, Cdh1, Ifrd1, Mxd1, and Timp1) based on the trajectory analysis of tumor cells can affect the survival of tumor patients." (PMID 38539232, 2024). "If IFRD1 expression remains consistently elevated, it contributes to enhanced tumor survival, thereby indicating a more unfavorable prognosis when there is higher expression of IFRD1." (PMID 38802351, 2024). "IFRD1 was significantly (p = 2.276951 × 10−3) higher in the normal tissue than the tumor tissue, whereas IFR6 was high in tumors in comparison with normal tissues (p = 3.386823 × 10−4)." (PMID 39765744, 2024). "Knockdown of IFRD1 results in an increased production of pro-inflammatory cytokines and chemokines by tumour cells when stimulated with IFN-γ and TNF-α." (PMID 26055519, 2015). "Our data suggest that EGFR-driven overexpression of IFRD1 may also play a role in deregulating NFκB-signalling in HPV-induced tumour cells." (PMID 26055519, 2015). "However, the mice maintained on glutamine-deficient diet exhibited significantly decreased tumor volume and weights of IFRD1 knockout tumors but not WT tumors." (PMID 38802351, 2024). "These genes are involved in the regulation of immune/inflammatory response (Lgals1, Ptgds, Tff2, Ubd), tumor angiogenesis (Lgals1, Esm1, Ndrg1), epidermal growth factor signaling (Erbb4, Nrg1), response to tissue injury (Tff2, Vnn1), and gene transcription (Id3, Ifrd1)." (PMID 19340302, 2009). "Neither IFRD1 deletion nor CB-839 treatment showed antitumor activity as monotherapies, but application together resulted in significant retardation of tumor growth." (PMID 38802351, 2024).
infection (4 papers, 2011 to 2025). The state of being infected such as from the introduction of a foreign agent such as serum, vaccine, antigenic substance or organism. "In the case of HPV, it has been shown that infection drives IFRD1 expression, which is then accompanied by a decrease in proinflammatory signaling." (PMID 40815167, 2025). "Reciprocally, when undifferentiated KCs were infected with native HPV16 virions, IFRD1 mRNA (right) and IFRD1 protein (right) levels were clearly enhanced after 2 days of infection." (PMID 26055519, 2015). "Indeed, the computed top DEG, typifying each cluster on day 3 in the effector phase of infection, hosted several interferon-induced anti-viral genes (Irf1, Irf7, Ifrd1, Socs1, Socs3, Ifit1, Bst2, and Isg15) as well as genes associated with mature resident Trm cells (Cd69, Nfkbid, Brd2, FosB)." (PMID 35260804, 2022). "Thus, hrHPV upregulates the expression of IFRD1 soon after infection, thereby effectively decreasing the basal levels of transcriptionally active RelA and as a consequence the levels of pro-inflammatory cytokines induced via various innate and adaptive immune-mediated NFκB stimulatory pathways." (PMID 26055519, 2015).
IFRD1 also shares sentences with these, for which no sentence is quoted: influenza (3 papers); abdominal aortic aneurysm (1); atherosclerosis (1); brain ischemia (1); cervical cancer (1); Dystonia (1); glioblastoma (1); Hypoglycemia (1); invasive breast carcinoma (1); metabolic disease (1); prostate carcinoma (1); psoriasis (1); skin cancer (1); squamous cell carcinoma (1).